PPARA (peroxisome proliferator activated receptor alpha)
Diseases named in the same sentence as PPARA in open-access papers (continued):
Sharing a sentence is not in itself a finding about the gene and the disease.
cancer (continued). "In a mouse melanoma model, tumour progression was delayed by the combination of a PPARα agonist and a cancer vaccine." (PMID 38245525, 2024). "PPARs are nuclear hormone receptors, including PPARα, PPARδ, and PPARγ, which are important in regulating cancer cell proliferation, survival, apoptosis, and tumor growth." (PMID 39660001, 2024). "PPARα was activated in pancreatic and colorectal CSCs in which lipid droplets accumulated, and PPARα inhibition suppressed cancer stemness." (PMID 39519311, 2024). "Both CPT1A and CPT1B isoforms of CPT1 are now known to function as downstream target genes for PPARα regulation in many cancers." (PMID 39596847, 2024). "For example, APOE, PLAU, CDK1 and MUC1 were significantly higher in TNBC tissues than in cancer-parasite tissues, whereas PDGFRB, RET, ROCK2, CCND1 and PPARA were significantly lower in TNBC tissues than in cancer-parasite tissues." (PMID 38329441, 2024). "Reduced PPARG and PPARA expression have also been documented in some cancers through micro RNAs (miRNAs), long non-coding RNAs (lncRNAs), and promoter hypermethylation." (PMID 39195246, 2024). "We are intrigued by the extensive and diverse role of PPARα, which encompasses metabolic disorders and cancer." (PMID 38004166, 2023). "This highlights the potential for developing specific synthetic ligand targeting PPARα as a novel approach for cancer treatment." (PMID 38189049, 2023). "PPARα agonists like fenofibrate and WY-14,643 have been found to inhibit tumor growth in multiple cancer studies and are potential targets for treating various malignancies." (PMID 38189049, 2023). "Overall, the role of PPARα in tumor/cancer development predominates among pesticides that have been reported to be able to do so by enabling the activation of genes that allow peroxisome proliferation and function." (PMID 36875280, 2023). "While the role of PPARα in fatty acid metabolism is well recognized in both human and rodents, its role in cancer shows high species-specificity." (PMID 36982734, 2023). "The mechanism of action by which PP pesticides are capable of producing tumors/cancer has been extensively studied, and the role of PPARα activation appears to be important in this process; even though, the results in rodents are not applicable to humans." (PMID 36875280, 2023). "Some literature reports even suggest the use of PPARα activators, such as Wyeth-14,643, another hypolipidemic chemical and potent peroxisome proliferator, to prevent and treat certain types of human cancer." (PMID 36982734, 2023). "The antitumour effect of PPARα and PPARγ in various types of cancers, both in laboratory and in clinical settings, have been recently reviewed." (PMID 36982753, 2023). "EGCG exerted its beneficial anticancer effects via PPARα activation and inactivation of HO-1/Nrf2 pathway on some cancer cell lines, including pancreatic, esophageal, MCF-7, and ovarian." (PMID 36092543, 2022). "Although the anti-hyperlipidemic activity of fenofibrate is understood to occur through PPARα, the mechanisms responsible for the drug’s potent anti-cancer activity in HPV+ HNSCC are unclear." (PMID 35053444, 2022). "The agonism of peroxisome proliferator-activated receptor-α (PPARα) via ligands, including WY-14,643, has been considered a promising intervention for cancers." (PMID 36384580, 2022). "Lastly, to assess the contribution of PPARα and γ on cancer cell growth and invasion in vivo, GW6471 was administered daily, with or without ABT pre-treatment." (PMID 34984327, 2022). "Nevertheless, a recent study evidenced that PPARα drives dendritic-cell immune dysfunction in cancer." (PMID 35954274, 2022). "We also found a correlation between G6PD expression and the PI3K/AKT signalling pathway in cancer, the PPARα pathway, glycolysis, and gluconeogenesis, suggesting a correlation with tumour proliferation." (PMID 35712981, 2022).
cancer (continued). "Conjugated linoleic acids induced apoptosis in a variety of human cancer cell lines, which was accompanied by a strong increase in PPARα." (PMID 35954274, 2022). "In line with this, the positive transcriptional regulation of CPT1C by PPARα was shown to inhibit senescence in different cancer cell lines in vitro." (PMID 35954274, 2022). "The synergistic pro-apoptotic anticancer activity of clioquinol (5-chloro-7-iodo-8-hydroxyquinoline) and docosahexaenoic acid (DHA) in human cancer cells has also been suggested to be mediated by PPARα signaling." (PMID 35954274, 2022). "presented the role of the Peroxisome proliferator-activated receptor alpha (PPAR-α)/ATGL axis in cancer." (PMID 35912266, 2022). "The tumoricidal effects of several PPARα agonists have already been extensively evaluated in different cancer types." (PMID 39872079, 2022). "The role of PPARα in different cancers still needs further exploration; its contradicting function in some research indicates that the function of this factor might be tightly associated with metabolic states, or even the regulation of PPARα is only a consequence of therapies." (PMID 36589809, 2022). "TCGA data suggest that tumor microenvironment characteristics were correlated with the expression level of PPARα in pan-cancer." (PMID 36589809, 2022). "Many early phase clinical trials have been conducted to examine the clinical feasibility of PPAR agonists, particularly PPARα and PPARγ agonists, against a wide range of cancers." (PMID 33946986, 2021). "The results obtained point toward using a PPARα antagonist as an adjuvant agent to prevent cancer stem cell proliferation and invasiveness by altering the energetic metabolic pathways and blocking cell cycle progression." (PMID 33525605, 2021). "The PPARA antagonist TPST-1120 promotes a more inflamed TME in different types of cancer and is currently in clinical trial as a monotherapy and in combination with anti-PD-1 therapy." (PMID 34430923, 2021). "Analysis of the 48 common miRNAs indicated the enrichment in PPARα–related targets and other pathways related to liver injury and cancer." (PMID 34199666, 2021). "Clofibrate, a PPARα agonist, blocks heme oxygenase-1 (HO-1) induction and sensitizes cancer cells to EGCG-promoted cell death." (PMID 34445672, 2021). "Peroxisome proliferator‐activated receptor alpha (PPARA) is involved in the regulation of cancer progression." (PMID 34264003, 2021). "Accordingly, the protein levels of PPARα and PGC1α were detected by western blotting and were significantly decreased in both cancer groups, particularly in the Cd-Can group." (PMID 34876963, 2021). "Understanding the activation on PPARα, β/δ, and γ by different types of PFAS will provide insight on toxicity levels and how PFAS-associated cancers are initiated." (PMID 34836157, 2021). "Another pitfall in PPAR cancer research is that current drug development and research attention highly skew towards PPARα and PPARγ." (PMID 33946986, 2021). "PPAR has three different subtypes (PPARα, PPARβ/δ, and PPARγ) and has been shown to participate in the brain metastasis of cancer cells." (PMID 34530822, 2021). "MiRs has been shown to regulate PPARα, a known regulator of both adipogenesis and carcinogenesis, suggesting that miRNAs play a vital role between obesity and cancer." (PMID 34199293, 2021). "The activation of PPARα sensitizes cancer cells to epigallocatechin-3-gallate (EGCG) treatment by suppressing HO-1 expression." (PMID 34445672, 2021). "Of note, simultaneous inhibition of TAG synthesis and lipolysis, which produce fatty acids from LDs and activate PPARα, was more effective in reducing cancer stemness." (PMID 33466690, 2021). "This suggested that TAG turnover strengthens the maintenance of cancer stemness through PPARα activation." (PMID 33466690, 2021).
cancer (continued). "Recently, the potential role of PPARA in other pathological conditions, such as cancers, has been recognized." (PMID 33959155, 2021). "Reported studies in cancer cells revealed that EGCG induced the expression level of PPARα protein in a dose-dependent manner." (PMID 34445672, 2021). "PPARα antagonism inhibits several pivotal cancer-relevant metabolic pathways, leading to reduced tumour growth in RCC." (PMID 34358255, 2021). "PPARα-dependent and PPARα-independent signaling is involved in cancer cell reactions to FF; however, the interference of FF with the chemoresistance of cancer cells has not yet been analyzed." (PMID 30641904, 2019). "Previous studies have shown that PPARα and PPARγ agonists suppress tumor growth in different cancer cells by angiogenesis inhibition." (PMID 31089369, 2019). "Analysis of the BSCE database suggested the molecular mechanisms by which digoxin suppresses the proliferation of cancer cells include the caspase cascade in apoptosis and peroxisome proliferator-activated receptor α (PPARα) pathways." (PMID 31719612, 2019). "Of the inversely correlated canonical pathways between digoxin and cancers, the “Caspase cascade in apoptosis,” “Genes involved in Cell Cycle Checkpoints,” and “Mechanism of Gene Regulation by Peroxisome Proliferators via PPARα” were observed." (PMID 31719612, 2019). "Taken together, PPARα/Bcl2/autophagy signaling promoted autophagy and enhanced tumor suppression and chemotherapy sensitivity to cancer cells." (PMID 30519260, 2018). "PPARα is aberrantly expressed in various cancers, and activated PPARα inhibits the proliferation of some tumor cells." (PMID 29862267, 2018). "There are several evidences about the tumor suppression role of PPARα and PPARγ, but there are also several evidences about their cancer promotion activity; instead, regarding PPARβ/δ, the majority of study conducted shows its oncogenic role." (PMID 29966227, 2018). "PPARα (peroxisome-proliferator-activated receptor α) plays a critical role in regulation of inflammation and cancer, while the regulatory mechanism of PPARα on cancer cell autophagy is still unclear." (PMID 30519260, 2018). "The synthetic ligands of PPARα including fenofibrate, clofibrate, and wyeth suppress cancer cell proliferation." (PMID 30519260, 2018). "Among the 606 cancer-related miRNAs, eight were targeting PPARα, four were targeting PPARβ/δ, and eight were targeting PPARγ." (PMID 28167956, 2017). "Increasing literatures show that PPARα or PPARγ can inhibit tumor progression by multiple pathways, which can be the potential therapeutic targets for cancer treatment, while some agonists suppress tumor progression in a PPARα/γ- independent manner." (PMID 28948004, 2017). "Tumor suppression by PPARα agonists has been reported in some cancers, while PPARα overexpression has been found to lead to progression in other cancers." (PMID 28594934, 2017). "Peroxisome-proliferator-activated receptors (PPARs) are nuclear hormone receptors including PPARα, PPARδ and PPARγ, which play an important role in regulating cancer cell proliferation, survival, apoptosis, and tumor growth." (PMID 28948004, 2017). "Nonetheless, in other cancers, including kidney and hepatocellular carcinoma, PPARα has also been found to lead to the progression of tumor growth." (PMID 27835866, 2016). "The link between PPARα and cancer was first made after PPARα agonists were shown to increase the incidence of liver tumors in rodents." (PMID 27835866, 2016). "Cyclin D1 down-regulates the expression of numerous PPARα target genes and inhibits fatty acid (FA) oxidation in both hepatic cells and in a variety of cancer cell lines." (PMID 27351284, 2016).
cancer (continued). "In hepatocytes, AML12 cells, and the cancer cell lines used in our studies, mitogenic stimulation led to decreased PPARα activity and FA oxidation." (PMID 27351284, 2016). "Although it is present in highest abundance in organs involved in lipid catabolism (such as the liver), PPARα is detectable in a variety of cancer cell types." (PMID 27351284, 2016). "PPARα agonist drugs inhibit proliferation, decrease invasiveness, and/or trigger apoptosis in cancer cell lines derived from breast, endometrial, lymphatic, central nervous system, and other malignancies." (PMID 27351284, 2016). "The investigated pirinixic acid derivatives modulate 5-LO, mPGES1, PPARα, and PPARγ at varying potencies and these molecules are considered as potential anti-cancer drug targets." (PMID 26887049, 2016). "An in vitro study in 2006 showed that PPARα ligands inhibit cancer cell growth and several subsequent studies have shown that PPARα activation inhibits tumor growth." (PMID 25734181, 2015). "Taken together, PPARα functions as an E3 ubiquitin ligase to induce Bcl2 ubiquitination and degradation, leading to increased cancer cell sensitivity in response to chemotherapy drugs." (PMID 26556865, 2015). "Further analysis shows that PPARα significantly increased cancer cell sensitivity in response to chemotherapy drugs." (PMID 26556865, 2015). "We hope our findings will help in further development and improvement of anti-cancer therapy using already approved PPARα agonists." (PMID 26122096, 2015). "Peroxisome proliferator-activated receptor alpha (PPARα) ligands have been reported to suppress cancer growth." (PMID 25327562, 2014). "Despite extensive knowledge of the various targets of PPARα, the precise role of this receptor in regulation of cancer is still uncertain." (PMID 23951092, 2013). "It is possible that these events are related to energy metabolism alterations which have been well studied in normal cells and in many diseases, including cardiovascular diseases and cancer, in which PPARα has been suggested as a therapeutic target." (PMID 23951092, 2013). "PPARα remains a viable target for the treatment and prevention of cancer because of evidence indicating that humans are refractory to the hepatocarcinogenic effects of PPARα agonists." (PMID 22966221, 2012). "PPARα leads to carcinoma from fatty liver through these genes (fatty acid translocase (FAT) and fatty acid transport protein (FATP))." (PMID 23316217, 2012). "Analysis of downregulated miRNAs in ASCs revealed significant involvement of the canonic pathways, including molecular mechanisms of cancer, axonal guidance signaling, ephrin receptor signaling, and PPARα/RXRα activation." (PMID 22169120, 2011). "Cancer formation after PPARα activation in tissues other than the liver has been described in rats and includes testicular (Ledig cell) and pancreatic acinar cell tumors." (PMID 20847941, 2010). "For instance, PPARα regulates the expression of miRNA let-7C in hepatocytes, a tumor suppressor gene that regulates cancer cell proliferation." (PMID 19125181, 2008). "Concerning to the involvementof the PPARα form and its ligands in cancer, both tumorpromotion and suppression properties have been reported." (PMID 18670614, 2008). "While PPARα was the first PPAR to be associated with tumorigenesis, the emerging awareness of the PPARγ-cancer connection is evidenced by the fact that 4 out of 7 reviews in this issue focus on PPARγ." (PMID 19590598, 2008). "These doses are typical of those used in rodent cancer studies with PPARα agonists but higher than the low part-per-billion PFOA concentrations measured in human and environmental samples." (PMID 18709148, 2008). "Specifically, we believe that establishing cause-effectrelationships between early biomarkers and later cancer development is key tounderstand the mode of action for carcinogenic effects of dual-acting PPARα+γagonists in the rat urothelium." (PMID 19197366, 2008).
cancer (continued). "The expression of bothUCP2 and UCP3 is regulated by PPARα, and this notion provides an interesting linkwith cancer cell metabolism and behavior." (PMID 18509489, 2008). "PPARα activation can target cancer cells energy balance by blocking fatty acid synthesis and by promoting fatty acid β-oxidation." (PMID 18509489, 2008). "The prevalence of survival over proliferation was confirmed by Bcl-2 or Bcl-XL increase in cancer versus mucosa, and by decreased PPARα." (PMID 17389773, 2007). "It has been proposed that PPARα agonists stimulate Kupffer cells in rodents which in turn, release mitogenic factors leading to hepatic hyperplasia, and eventually cancer." (PMID 17129391, 2006). "The initial indication that the PPARs are involved in the aetiology of cancer was the isolation of PPARα as the mediator of the tumour-promoting effect of peroxisome proliferators, compounds that cause heptocellular carcinoma in rodents." (PMID 15583697, 2005). "However, this increase was significantly diminished when cancer cells were cocultured with CCR2‐ or PPARα‐silenced ADSCs." (PMID 41160815, 2026). "Therefore, our results substantiate the role of FFAs provided by adipocytes in inducing ANGPTL4 expression in cancer cells by acting as ligands for PPARα." (PMID 40616161, 2025). "Interleukin 6 (IL-6), enriched in cancer-associated adipocytes, and lipolysis-derived free fatty acids (FFAs) released from adipocytes, amplify ANGPTL4-mediated glycolysis and metastasis through activation of STAT3 and PPARα pathways in TNBC cells." (PMID 40616161, 2025). "We hypothesize that the release of the cancer-related active ingredient S1P by LSEC necessitates inhibition of the key molecules PPARα and CPT-1A under mechanical stress, acting as a protective measure to fulfill sphingolipid biosynthesis demands." (PMID 41039598, 2025). "Additionally, it is noteworthy that PPARα has been reported to suppress HIF1α protein expression in cancer cells, despite HIF1α being critical for the regulation of glycolysis in living cells." (PMID 40616161, 2025). "Moreover, emerging evidence suggests that PPARα inhibits tumor progression by regulating multiple signaling pathways, making it a potential therapeutic target for cancer treatment 42-44." (PMID 40959276, 2025). "Consequently, by exploiting the sensitivity of cancer cells to PPARα inhibition, PPARα inhibitors can impede this metabolic process for antitumor purposes." (PMID 39875357, 2025). "Hence, this study found that ether-lipids promote cancer cell migration potentially via PPARα downregulation, leading to impaired lipophagy, thus blocking lipid clearance and resulting in ether-lipid accumulation." (PMID 40936093, 2025). "Hence, the activation of PPARα in KAIMRC1 cells indicates that these cancer cells utilize an endogenous ligand to activate the receptor and initiate its signal." (PMID 39859448, 2025). "However, other studies have shown that RAE1 promotes cancer progression by regulating peroxisome proliferator-activated receptor alpha (PPARα)-mediated lipid metabolism and regulating EMT signals." (PMID 39080077, 2024). "Recent studies have highlighted the importance of PPARα modulators for cancer therapy." (PMID 38097734, 2024). "On one hand, blocking PPARα inhibits the proliferation of breast and ampullary cancer." (PMID 38097734, 2024). "There is evidence that accumulation of LDs activates PPARα in CSCs to sustain cancer stemness." (PMID 38561775, 2024). "Other widely studied NRs, PPARα, PPARβ/δ and PPARγ, play important roles in both cancer progression and inhibition via modulation of metabolism, inflammation, cell proliferation and apoptosis in various cancer types in a context-dependent manner." (PMID 39199690, 2024). "PPARα transcription factor regulates fatty acid oxidation and inflammation in many cancers." (PMID 39660001, 2024).